INS (insulin)
Diseases named in the same sentence as INS in open-access papers (continued):
Sharing a sentence is not in itself a finding about the gene and the disease.
Hyperinsulinemia (continued). "Depletion of PPARβ in mice increased pancreatic β-cell mass and improved insulin secretion causing hyperinsulinemia." (PMID 37126142, 2023). "Dysregulation of insulin and glucose metabolism are important candidate mechanisms and hyperinsulinemia itself has been causally linked to colorectal cancer development; however, the precise mechanisms linking these phenomena are not clear." (PMID 37365285, 2023). "A heterozygous Arg274His mutation of AKT2 gives rise to a blocked impact on insulin activity, which was observed in patients with severe postprandial hyperinsulinemia." (PMID 37664840, 2023). "The combination of overfeeding and DHT treatment caused hyperinsulinemia and decreased systemic insulin sensitivity." (PMID 37371678, 2023). "Too much drives the condition hyperinsulinemia, strongly associated with chronic diseases and ageing, as insulin prevents cells from being able to commit controlled cellular “self-destruction” apoptosis when they should." (PMID 37760052, 2023). "Impaired insulin signaling associated hyperinsulinemia can lead to visceral fat accumulation, which is associated with several metabolic diseases and renal filtration barriers injury." (PMID 36761214, 2023). "In order to counteract this IR, the beta cells in the islet of Langerhans produce more insulin, which causes hyperinsulinemia.The pancreatic beta cells' capacity to produce insulin is limiting." (PMID 37814679, 2023). "Paradoxically, hyperinsulinemia makes things worse by causing insulin receptor downregulation and activating a vicious cycle of gradually increasing compensatory insulin levels and decreased insulin signaling." (PMID 37524865, 2023). "As insulin directly mimics the action of LH and indirectly raises GnRH, hyperinsulinemia is the primary cause of excessive androgen production." (PMID 36835989, 2023). "EDIH predicts hyperinsulinemia using C-peptide concentration that involves food groups associated with insulin biomarker responses based on dietary intake over the long term." (PMID 38082394, 2023). "It is worth noting that PHHI is associated with hyperinsulinemia, and T206M exhibited the highest HOMAβ and fasting immunoreactive insulin (FIRI) values among thirty Japanese MODY2 patients." (PMID 37958824, 2023). "Insulin plays an important role in regulating uterine metabolism during pregnancy, and hyperinsulinemia is associated with conditions impacting fertility." (PMID 37170094, 2023). "Increased skeletal-muscle insulin resistance stimulates a compensatory increase in pancreatic insulin secretion, causing beta cell hypertrophy and hyperinsulinemia." (PMID 37299553, 2023). "Insulin resistance, another established cancer risk factor, causes high amounts of insulin, or hyperinsulinemia, which occurs before the onset of type 2 diabetes." (PMID 36672434, 2023). "Hyperinsulinemia in the offspring of various animals has been linked to transference of breast milk hormones such as insulin and leptin." (PMID 37899888, 2023). "Excess selenium intake impairs insulin-stimulated signaling to cause glucose tolerance, hyperinsulinemia, and hypertension." (PMID 36761214, 2023). "Due to IR, the compensatory mechanism is activated, in which pancreatic β-cells increase insulin production, causing hyperinsulinemia." (PMID 37372966, 2023). "Hyperinsulinemia is associated with a higher risk of breast cancer, as demonstrated in a case-cohort study by Gunter in 2015, in which the authors showed that insulin levels were positively associated with breast cancer development in postmenopausal women." (PMID 36902406, 2023). "Hyperinsulinemia and hypersensitivity of the ovarian cyst to insulin cause an increase in free androgen levels." (PMID 38024815, 2023). "We also identified four different mechanisms underlying impaired insulin sensitivity and increased risk of T2D, or diabetogenic hyperinsulinemia." (PMID 37790568, 2023).
Hyperinsulinemia (continued). "By improving insulin sensitivity, melatonin can help manage hyperinsulinemia, a common issue in PCOS, and ameliorate associated metabolic abnormalities." (PMID 38106751, 2023). "Because of this increased compensation by producing more insulin and amylin, there would also be an increased risk of islet amyloid deposition due to the amyloidogenic hyperamylinemia and hyperinsulinemia, which are both common to IR of the MetS." (PMID 36984562, 2023). "Using HOMA tests, we demonstrated that CP is associated with a 50% reduction in insulin sensitivity, partially compensatory hyperinsulinemia, and a decreased %BxS vs controls, even after adjustment of BMI." (PMID 36651310, 2023). "The early stages of T2D are associated with hyperinsulinemia, but plasma insulin levels steadily drop as β-cell dysfunction progresses." (PMID 37524865, 2023). "Conversely, although fasting plasma insulin levels were elevated in fat-fed mice lacking MBOAT7 in hepatocytes, deletion of MBOAT7 in adipocytes caused hyperinsulinemia and reduced insulin sensitivity, with only minor effects on the liver fat." (PMID 37127068, 2023). "Hyperinsulinemia resulting from increased insulin production and reduced insulin clearance is associated with hepatic IR." (PMID 37671098, 2023). "Its association with the insulin signaling pathway and hyperinsulinemia, along with being part of the carbohydrate absorption, glycolysis, fructose and mannose metabolism pathways further emphasizes the statistically inferred causality relation." (PMID 37679740, 2023). "It has been shown that chronic insulin exposure can induce leptin secretion and production and hyperinsulinemia causes leptin resistance in hippocampal neurons." (PMID 38068822, 2023). "In an adult patient, endogenous hyperinsulinism is mainly caused by insulinoma, functional β-cell disorders, insulin autoimmune hypoglycemia (Hirata’s disease), or insulin secretagogues." (PMID 37371827, 2023). "Hyperinsulinism and hypogonadism are considered as the capability of insulin to stimulate gonadal and adrenal androgen production, and this hyperinsulinism is also one of the major risk factors of PCOS." (PMID 36648830, 2023). "Hyperinsulinemia led to a decreased susceptibility of 4E-BP1(Thr37/46) for phosphorylation upon acute insulin stimulus." (PMID 36386326, 2022). "It has recently been demonstrated that hyperinsulinemia induces a premature senescent transcriptomic and secretory profile in mature adipocytes and also causes insulin resistance in neurons resulting in a senescence-like phenotype." (PMID 35872305, 2022). "In contrast, equine ID is rarely associated with insufficient insulin release but rather excessive postprandial hyperinsulinemia." (PMID 35978710, 2022). "Whereas the loss of Ceacam1 by <50% promotes fatty acid β-oxidation, its progressive loss by >50% (after about 3–4 weeks) represses hepatic insulin clearance to cause chronic hyperinsulinemia and ensuing hepatic steatosis and hepatic insulin resistance." (PMID 36009446, 2022). "Hyperinsulinemia is a term for chronically high levels of circulating insulin, which is typically linked to obesity and T2DM." (PMID 35457158, 2022). "Post-meal hyperinsulinemia several years after GB is caused by augmented insulin secretion and, possibly, a reduced insulin clearance rate (ICR)." (PMID 35887007, 2022). "Cardiomyocytes are typical insulin-targeted cells, and hyperinsulinemia caused by IR will have a direct nutritional effect on the myocardium, that is, increases the mass of myocardium and decreases the cardiac output." (PMID 35715813, 2022). "Consistently, chronic hyperprolactinemia has been associated with impaired insulin secretion, characterized by postprandial hyperinsulinemia and exceeding insulin secretory response to glucose in humans." (PMID 36237192, 2022).
Hyperinsulinemia (continued). "In patients with impaired glucose tolerance, the basic defect is postulated to be the loss of normal insulin sensitivity, leading to compensatory hyperinsulinemia and increased VLDL-TG secretion." (PMID 35923815, 2022). "On the other hand, HC feeding was globally associated with hyperinsulinemia, mainly driven by significant increases in serum insulin levels in male rats fed HC diet for 12 or 24 weeks compared to their NC-fed counterparts." (PMID 35814210, 2022). "The main paradox in the pathophysiological link between hyperandrogenemia and hyperinsulinemia in PCOS is the ovarian susceptibility to insulin activity (leading to androgen production) despite systemic insulin resistance." (PMID 36009364, 2022). "Decreased apoptosis of stromal cells was observed in early pregnant insulin-exposed mice, in which the decidualization process was markedly compromised In light of these observations, hyperinsulinemia and IR are linked to poor fertility." (PMID 35784578, 2022). "Insulin dysregulation (ID) is associated with increased risk of laminitis in horses and experimental evidence suggests that hyperinsulinemia directly leads to lamellar damage possibly via activating insulin-like growth factor (IGF-1)." (PMID 35906619, 2022). "There is limited research to confirm diagnostic thresholds for hyperinsulinemia in to insulin metabolism become potentially harmful are needed." (PMID 36733795, 2022). "This condition leads to high levels of circulating insulin (hyperinsulinemia) that are associated with hyperglycemia." (PMID 35741464, 2022). "Treatment of cells with pathologic concentrations of TNFα or with high nutrients also caused a decrease in insulin-stimulated IR incorporation into puncta similar to that observed for hyperinsulinemia." (PMID 36473871, 2022). "IR and hyperinsulinemia are suggested to be associated with an increase in the secretion and decrease of the extracellular clearance of Aβ as a result of reduced insulin-degrading enzyme system (IDE) synthesis." (PMID 35682821, 2022). "In general, aging is characterized by chronic hyperinsulinemia that is associated with reduced expression of insulin receptors and impaired insulin signaling cascades (i.e., insulin resistance)." (PMID 35164216, 2022). "Hyperinsulinemia reportedly causes the failure of insulin secretion regulation, and the rapid proliferation and metastasis of cancer cells is promoted by an increase in the biological activity of insulin-like growth factor 1 (IGF-1)." (PMID 35887596, 2022). "Solid evidence indicates that insulin causes sodium and water retention, and both endogenous and exogenous hyperinsulinemia have been correlated to increased blood pressure." (PMID 36289636, 2022). "Insulin is known to have a promitotic effect and in vivo experiments have shown that dietary hyperinsulinemia is associated with cell proliferation and tumor growth." (PMID 35184245, 2022). "A vicious cycle resulting from binge eating can lead to hyperinsulinemia and high serum insulin levels can cause a sense of hunger, thereby promoting the generation and accumulation of adipose tissue." (PMID 36699697, 2022). "The main features of T2DM are hyperinsulinemia, IR, and defective insulin secretion caused by β-cell failure." (PMID 36147580, 2022). "In Sx16 knockout cells, hyperinsulinemia resulted in a dramatic elevation in basal glucose uptake, and a complete loss of insulin-stimulated transport." (PMID 36467416, 2022). "The study in addition showed increased body and organ weights, 1-hour postload glucose, reduced insulin sensitivity and caused hyperinsulinemia." (PMID 35881588, 2022). "Chronic inflammation in T2DM is associated with progressing cardiovascular risk factors and is also one of the leading players in insulin function, resulting in hyperinsulinemia." (PMID 35733163, 2022).
Hyperinsulinemia (continued). "For instance, hyperinsulinemia is an independent risk factor for BC and the insulin/insulin receptor (IR) axis is involved in BC growth and metastasis." (PMID 35672854, 2022). "In T2DM, hyperinsulinemia is closely associated with dysregulated insulin secretion and chronically elevated insulin levels in the bloodstream." (PMID 36235831, 2022). "This condition is probably caused by a state of hyperinsulinemia, where insulin acts as a cofactor in the erythropoiesis process, resulting in an increase in the RBC value." (PMID 35497944, 2022). "Persistent systemic hyperinsulinemia is also regarded as a cardiovascular risk factor and in part, this risk is ascribed to the arm of insulin signal transduction that mediates mitogenic actions." (PMID 35177603, 2022). "Hyperinsulinemia is a compensatory increase in pancreatic insulin production caused by skeletal muscle insulin resistance." (PMID 35547584, 2022). "Although some studies have shown the role of hyperinsulinemia in different cancer types, the long-term risk of exposure to high levels of insulin, especially to high levels of post-challenge insulin for cancer development is relatively understudied." (PMID 35256755, 2022). "Under physiological conditions, insulin stimulates the uptake of glucose into the cardiac muscle to maintain glucose homeostasis; however, insulin insistence (IR) and hyperinsulinemia are associated with the metabolic disorder in cardiovascular diseases." (PMID 35656019, 2022). "We demonstrated that the variants result in a loss of repression of HK1 in pancreatic beta-cells, thereby causing insulin secretion and congenital hyperinsulinism." (PMID 36333503, 2022). "Although Kcnj11 +/− mice display hyperinsulinism, homozygous loss of the gene results only in transient hyperinsulinemia in neonates, unexpectedly followed by loss of insulin secretion and glucose intolerance in adulthood." (PMID 35008927, 2022). "Congenital hyperinsulinism mutations in genes related with the regulation of insulin secretion have been described." (PMID 36294341, 2022). "Congenital hyperinsulinism is a rare disease with a significant genetic component causing unregulated overproduction of insulin through defects in the insulin-releasing pathway." (PMID 36237195, 2022). "Due to the low quality of the first insulin which caused production of antibodies, high doses of insulin were required, leading to overtreatment/exogenous hyperinsulinemia." (PMID 33681089, 2021). "As hyperinsulinemia and hyperandrogenism are associated in clinical conditions, we aimed to investigate the interaction between insulin and androgens on decidualization." (PMID 34463022, 2021). "A comprehensive comparison of the associations of glucose, insulin, and Pro levels with arteriosclerosis showed hyperinsulinemia and hyperproinsulinemia on the OGTT to be related to coronary arteriosclerosis." (PMID 34518649, 2021). "Prolonged hyperinsulinemia is associated with a high incidence of endocrinopathic laminitis (also known as insulin-associated laminitis), a painful and debilitating hoof condition, which in severe cases can necessitate euthanasia." (PMID 33509165, 2021). "Each quartile increment of the fifth pattern, characterized by fructose, vitamins A and C, pyridoxine, and potassium, associated with the reduced risk of hyperinsulinemia, IR, and insulin insensitivity." (PMID 33499915, 2021). "In summary, hepatic insulin clearance is negatively associated with hepatic TG content and is an important determinator of systemic hyperinsulinemia seen in conditions characterized by excess hepatic TG accumulation." (PMID 33498493, 2021). "In this study, we aim to assess the association of EDIH and ELIH with the risk of IR, hyperinsulinemia, insulin sensitivity, and β-cell dysfunction in Iranian adults." (PMID 33985566, 2021). "In insulin-resistant obese with normal glycaemia from the MD-Lipolysis study, hyperinsulinemia was associated with elevated FFA." (PMID 33712379, 2021).
Hyperinsulinemia (continued). "Intracellular lipid content in the liver also decreases insulin clearance, causing the hyperinsulinemia, which is a sign of prediabetes." (PMID 34463983, 2021). "The connection between insulin and BC risk has been shown in several meta-analyses, suggesting that hyperinsulinemia and elevated basal insulin levels increase BC risk and are a negative predictor of BC prognosis." (PMID 33815289, 2021). "Increased insulin production or hyperinsulinemia has been largely associated with pancreatic cancer progression, but the molecular mechanisms associated with it have not been clearly elucidated." (PMID 34907162, 2021). "Prolonged fasting will also result in longer periods of time where insulin levels are low, potentially assisting in weight loss and improved insulin sensitivity through reduction in hyperinsulinemia." (PMID 34371888, 2021). "Many abnormalities in PCOS are related to the abnormal insulin levels, and hyperinsulinemia is considered as an independent cardiometabolic risk factor." (PMID 33584143, 2021). "For example, maternal obesity and early childhood obesity cause hyperinsulinemia and hyperleptinemia combined with insulin- and leptin-insensitivity." (PMID 34211985, 2021). "As a result, the pancreas β-cells respond to this condition by increasing the secretion of insulin into the circulation, causing hyperinsulinemia (High insulin concentration in the blood] in order to maintain a normal blood glucose level." (PMID 33920079, 2021). "Another, very important mechanism of antiandrogenic action of MF is largely due to an MF-induced increase in insulin sensitivity and consequent weakening of compensatory hyperinsulinemia, the main pathogenic factor in PCOS, also closely associated with HA." (PMID 33429918, 2021). "On a mouse model with liver-specific igf-1 gene deletion (LID model), very low concentrations of cIGF-1, high concentrations of GH and hyperinsulinemia were observed, associated with muscle insulin insensitivity." (PMID 34208601, 2021). "The liver parenchyma is a major site for insulin clearance, and defects in this process can cause hyperinsulinemia and secondary resistance." (PMID 33494161, 2021). "Given that, it seems unlikely that the association of hyperinsulinemia with baPWV was due to fatty liver and impaired hepatic insulin clearance." (PMID 34518649, 2021). "Chronic hyperinsulinemia has an association with tumor promotion due to the oncogenic potentials of insulin by stimulating cellular signaling cascade or incrementing growth factor-related cell proliferation." (PMID 34758846, 2021). "Let's assume for a moment that the excessive glucose and insulin leads to hyperinsulinemia and this is the cause of IR." (PMID 34447776, 2021). "Our finding suggested that a higher ELIH score is associated with increased odds of IR, insulin insensitivity, hyperinsulinemia, and a decreased risk of β-cells dysfunction." (PMID 33985566, 2021). "Previous in vitro models mimicking hyperinsulinemia showed that high insulin leads to a global increase in chromatin-associated histone acetylation, in particular at H3K9." (PMID 34944721, 2021). "SerB24 (originally designated insulin Los Angeles) is associated with variable genetic penetrance with hyperinsulinemia." (PMID 34659132, 2021). "Field-based observations have highlighted that hyperinsulinemia induced laminitis in horses, which is strongly associated with ID; clinical laminitis has been observed to occur as a consequence of 48–72 h insulin infusion." (PMID 34947937, 2021). "Additional studies in AD patients have demonstrated an association between insulin levels and cerebral amyloid deposition, and, importantly, hyperinsulinemia doubles the risk of developing AD." (PMID 34206322, 2021). "Hyperinsulinemia, through an increased intraportal insulin concentration, causes an increase in hepatic IGF-I production, as seen in this study's results." (PMID 34239560, 2021).